RB1 (RB transcriptional corepressor 1)
Diseases named in the same sentence as RB1 in open-access papers (continued):
Sharing a sentence is not in itself a finding about the gene and the disease.
cancer (1,473 papers, 1994 to 2026). A tumor composed of atypical neoplastic, often pleomorphic cells that invade other tissues. "Clinical trials evaluating PARP inhibitors in RB1-deficient cancers (NCT03227042) are currently underway." (PMID 41541668, 2026). "Recurrent insertions were located near cancer-associated genes, including RB1, NEDD4, FTO, LAMA2, NOD1, and KCNB2, implicating LINE-1 activity in cis-regulatory remodeling of oncogenic pathways." (PMID 41681929, 2026). "These aggressive cancers mimic the altered expression patterns observed in tumors with structural genomic defects in the RB1 gene such as MTs and homozygous loss, which are frequently observed in human cancers." (PMID 40138429, 2025). "From a clinical perspective, RB1 deleterious mutations and deletions are associated with poor overall survival (OS) and response to chemotherapy in cancers such as those of the breast, lung, and prostate." (PMID 40138429, 2025). "The up-regulation of ACSL4 expression and enhancement of lipid peroxidation rate induced by RB1 loss further intensify cancer cell dependence on GPX4 for iron homeostasis blockade." (PMID 40746825, 2025). "The disease follows Knudson’s two-hit model: heritable forms (30–40% of cases) involve a germline RB1 mutation (M1) and a somatic second hit (M2), predisposing to bilateral/multifocal tumors and secondary cancers." (PMID 41009976, 2025). "This study offers a novel approach and sheds light on the possibility of selectively targeting RB1‐deficient cells in the treatment of various types of cancer." (PMID 40904703, 2025). "In fact, the possibility of using a synthetic lethality strategy to treat RB1 deficient cancer has been evaluated." (PMID 40904703, 2025). "In this context, RB1 loss induces very high spherogenic activity with enhanced expression of a cancer stem-like cell and pluripotent stem cell markers, however, without much enhancing cell proliferation." (PMID 40707487, 2025). "RB1 is a prototypic tumor suppressor gene that is frequently mutated and/or deleted in a variety of human cancers." (PMID 40138429, 2025). "Overall, NFYC-AS1 emerged as a cell cycle-regulating asRNA with dual action, holding therapeutic potential in different cancer types, including the very aggressive RB1-mutated tumors." (PMID 38467619, 2024). "This shift towards targeting downstream effectors holds the potential for enhancing therapeutic efficacy and achieving more precise treatment outcomes in RB1-mutated cancer patients." (PMID 38672640, 2024). "Studies investigating alternative RNA splicing dysregulation in RB1-deficient cancers highlight the therapeutic potential of targeting spliceosomal machinery." (PMID 38672640, 2024). "Its importance is further underscored by its involvement in various cancer types, where mutations or dysregulation of RB1 contribute to the initiation and progression of diverse cancers." (PMID 38672640, 2024). "Dysfunction of Rb1 is associated with a wide range of cancers, particularly retinoblastoma, osteosarcoma, and small-cell lung cancer." (PMID 39062026, 2024). "Here, we summarize five types of pharmacological inhibition potentially applicable in RB1-deficient cancers." (PMID 38672640, 2024).
cancer (continued). "The TSG RB1 encodes a transcriptional repressor protein Rb1 and is mutated recurrently across a wide variety of cancer types." (PMID 40994652, 2024). "As PARP is also involved in the repair of DNA damage, its inhibition in RB1- or PTEN-deficient cancer cells can lead to genomic instability and cell death." (PMID 38612819, 2024). "Mutations or dysregulation of RB1 are implicated in the development and progression of diverse cancers, making it a prime target for therapeutic intervention." (PMID 38672640, 2024). "RB1 loss/E2F activation increases the sensitivity of cancer cells to ferroptosis by up-regulating ACSL4 expression and PUFAs enrichment." (PMID 39544949, 2024). "Specifically, we place a particular emphasis on potential strategies for targeted therapy that exhibit superior efficacy in the treatment of RB1-deficient cancers, offering a focused exploration of promising avenues in the pursuit of precision medicine." (PMID 38672640, 2024). "A transcriptomic signature of RB1 loss was recently described to be associated with poor outcomes across cancer types." (PMID 38837893, 2024). "Studies investigating Aurora kinase inhibitors have shown potential in targeting RB1-deficient cancers, suggesting approaches for the development of more effective treatment strategies in oncology." (PMID 38672640, 2024). "Previous studies have reported that the loss of Skp2 was sufficient to prevent tumorigenesis in Rb1-deficient mice, supporting a dependent role for SKP2 in Rb1-inactivated cancers." (PMID 38355807, 2024). "Scientists strive to grasp the intricate role of RB1 in regulating various biological processes and molecular pathways to devise innovative therapeutic strategies tailored to RB1-deficient cancers." (PMID 38672640, 2024). "Among other causes, p16 overexpression in cancer cells has been related to RB1 loss of function, which prevents the CDKN2A locus silencing by Polycomb Repressor Complexes and trimethylation of lysine 27 on histone H3 by EZH2." (PMID 36453028, 2024). "Each of these inhibitors has been proven effective for different RB1-deficient cancer cells, indicating that targeting downstream effectors regulated by RB1 offers promising strategies for therapeutic intervention in RB1-mutated cancers." (PMID 38672640, 2024). "Given the widespread occurrence of loss-of-function mutations in RB1 observed across various human cancers, direct targeting of the RB1 protein presents significant challenges." (PMID 38672640, 2024). "Loss of RB1 protein function, commonly observed through RB1 mutations in aggressive cancers, leads to dysregulation of SKP2 activity, resulting in decreased levels of p27 and compromised cell cycle control." (PMID 38672640, 2024). "Given the central role of Rb in the negative regulation of the cell cycle, it becomes evident why loss-of-function mutations in the gene RB1 renders cells capable of transforming into cancer cells." (PMID 38473726, 2024). "In summary, the dysregulation of alternative RNA splicing, particularly in RB1-deficient cancers, emphasizes the therapeutic potential of targeting the splicing machinery." (PMID 38672640, 2024). "RB1 mutation status has an impact on the treatment response and clinical outcome in various types of cancer." (PMID 37917619, 2023). "In drug sensitivity analysis, we found that low expression of these four genes (TTN, ARID1A, KDM6A, and RB1) was positively associated with resistance to cancer therapeutics response portal (CTRP)." (PMID 37065485, 2023). "(2020) evaluated that Rb1 can reduce the expression levels of key inflammatory cytokines TNF-α and IL-6 in a cancer cachexia mouse model, this finding is consistent with our experiment, indicating that Rb1 can alleviate symptoms caused by inflammation." (PMID 37868069, 2023).
cancer (continued). "The loss of RB1, or disruption of its interaction with other cellular factors, is associated with a variety of human cancers." (PMID 37182173, 2023). "RB1 loss in these tumors was linked to distinctive collagen environments relative to the other tumors in each cancer type." (PMID 37414817, 2023). "Deletions in RB1, therefore, result in unchecked cellular proliferation and have been implicated in oncogenesis across a variety of human cancers." (PMID 37046760, 2023). "Other than deletion or mutation of the Rb1 gene, the most frequent mutation locus in human cancers that disables the RB pathway is the CDKN2A locus coding for the p16INK4a CDK inhibitor (CKI)." (PMID 38132337, 2023). "We performed a gene signature analysis on 935 gene sets consisting of cancer hallmark and canonical signaling pathways and identified high expression of cell cycle regulatory sets, E2F and RB1 targets, as significantly associated with shorter PFS." (PMID 37475004, 2023). "Accordingly, RB1 is one of the most frequently mutated and lost genes in various cancers, including PCa." (PMID 37183818, 2023). "We highlight possible therapeutic strategies that exploit this inherent vulnerability for targeting RB1-deficient, treatment-resistant cancer." (PMID 37183818, 2023). "Taken together, the results indicate the crucial role of CCL5 and CXCL10 in mediating T cell recruitment in RB1-deficient cancer cells." (PMID 37937640, 2023). "About 30% of cancers have mutations in the Rb1 gene, which promotes cell proliferation and tumorigenesis by activating E2F." (PMID 38132337, 2023). "Having shown conclusively the role of RB1 loss in enhancing the ferroptotic potential of cancer cells, the authors took a further step to decipher the underlying molecular mechanisms." (PMID 37183818, 2023). "In fact, E2F1-3 activity is deregulated in most cancers, mainly by their overexpression or in the context of RB1 mutations." (PMID 36982482, 2023). "Located on chromosome 13q14, spanning over a length of 190kbp, RB1 is the most important carrier of mutations in the malignant tumour affecting the retina of mostly young children." (PMID 37667345, 2023). "Hereditary retinoblastoma patients, for example, have increased risk of subsequent unrelated cancers, indicating that mutational inactivation of RB1 contributes to tumorigenesis in tissues beyond the retina." (PMID 35368709, 2022). "The discovery of the Retinoblastoma-associated protein 1 (Rb1) in the late 1970s was an important milestone in understanding cancer development." (PMID 35267571, 2022). "This establishes RB1 as a rare example where mutation of a single human gene is sufficient, or at least rate limiting, to cause a human cancer." (PMID 35368709, 2022).
cancer (continued). "HDAC2 facilitates the conversion from M-MDSCs to PMN-MDSCs as it directly binds to retinoblastoma gene (rb1) promoter and causes silencing of rb1 expression in cancer." (PMID 36569895, 2022). "This inhibitory regulation is impaired in most types of cancer either through alteration of Rb1 expression (deletion, mutation, epigenetic silencing) or more often through functional inactivation by CDK-stimulated hyperphosphorylation." (PMID 35267571, 2022). "On the one hand, radiation affects the growth of soft tissue and orbital bones, leading to mid-facial hypoplasia of Rb survival; on the other hand, it has been proved to increase the life-long risk of secondary cancers in children with Rb1 mutations." (PMID 36211113, 2022). "RB1 has been implicated uniquely in some cancer relevant cellular functions, including pluripotency and cancer lineage plasticity." (PMID 35368709, 2022). "pRb is encoded by RB1, a tumor suppressor gene, and its expression is diminished in a broad range of cancers." (PMID 36012673, 2022). "Several other studies have reported that loss-of-function mutations in the RB1 gene are common in several refractory cancers, such as SCLC and triple-negative breast cancer." (PMID 36163484, 2022). "RB1-mutated subclone was the prominent subclone and accounted approximately 65.6% of all cancer cells while the MAP2K4-mutated subclone played a minor role." (PMID 35267640, 2022). "Many of these genes and chemical inhibitor targets scored as SL partners for RB1 loss in either the human cancer cell line analysis or in human cancer samples, further confirming the validity of our approach." (PMID 33591981, 2021). "In this scenario, in sharp contrast to SUCLA2, loss of LATS2 generates certain growth advantages to RB1-deficient cancer." (PMID 34359636, 2021). "Cancer-associated genes such as RB1, AML1, and CMYC, which display synchrony in allelic replication in normal cells, have shown earlier replication timing and asynchronous allelic replication in neurofibromatosis type 1 (NF1), a cancer-predisposing syndrome." (PMID 34831011, 2021). "RB1 is also commonly mutated in several other cancers, including sarcomas, lung cancers, and triple-negative breast cancers." (PMID 33668093, 2021). "It is of interest to address if pharmacological enhancement of LATS2 function in RB1-deficient cancer is feasible." (PMID 34359636, 2021). "A recent study focusing on a neighboring gene that is often collaterally deleted together with RB1 revealed a pharmacologically targetable vulnerability in RB1-deficient cancers." (PMID 34359636, 2021).
cancer (continued). "In agreement with this, SKP2 scored as a SL partner for RB1-deficient cells in both cancer cell line analysis and human cancer patients." (PMID 33591981, 2021). "As RB1 function is lost in a wide variety of cancer types at varied stages, synthetic lethality screening in RB1-deficient cells needs to be extended to more varies of cancers." (PMID 34359636, 2021). "From each analysis, we selected the top 20 small molecule drugs that represent potential drugs for RB1-deficient cancers based on their inhibitory transcriptional effect on genes that function as RB1 SL partners." (PMID 33591981, 2021). "To identify therapeutically exploitable vulnerability linked to deleterious RB1 mutation we assessed the sensitivity of histotype-matched cancer cell line pairs differing in RB1 mutation status to clinical candidate agents that target DNA metabolic processes." (PMID 34862364, 2021). "In summary, our cross-species data integration based on data from the Drosophila eye screen and human cancer cell line screens identified 38 genes as potential therapeutic targets for RB1-deficient cancer cells." (PMID 33591981, 2021). "The RB1 gene has a role in proliferation and apoptosis and the alteration of RB1 underlies both cancer development and resistance to therapy." (PMID 33726790, 2021). "These observed similarities argue for a shared inability of cancers with HRd or RB1 loss to avert the lethal consequence of trapped PARP complexes, which is known to underlie PARPi inhibitor sensitivity caused by HRd." (PMID 34862364, 2021). "It is evident that RB1 genes are silenced in HCC, but different from other cancers, RB1 is rare to be mutated in HCC cells." (PMID 34336665, 2021). "The inactivation of RB1 is frequently assessed in triple-negative BC and is linked to sensitivity to many cancer drugs, including TOP1 inhibitors." (PMID 33670375, 2021). "Among these genes, RB1 stood out with intronic mis-splicing mutations in five different cancer types." (PMID 33420369, 2021). "Deficiency in terminal differentiation following RB1 inactivation would be another possible target in cancer treatment." (PMID 34359636, 2021). "Yet, a mosaic carrier has an increased risk of developing other malignant neoplasms, since a certain percentage of the cells possess the mutant RB1 allele." (PMID 34680218, 2021). "In some cancers, the RB1 gene is deleted or mutated such that both the canonical and non-canonical functions of RB are lost." (PMID 33668093, 2021). "Loss or mutation in the RB1 tumor suppressor gene; contributes to the development of many cancers, including cancers such as breast, bone, lung and bladder." (PMID 33407772, 2021). "In 5.8% of survivors, pathogenic or likely pathogenic variants were detected in specific cancer predisposition genes, e.g., Rb1, NF1, BRCA2." (PMID 34680213, 2021). "These class 2 (‘two-hit loss’) drivers include the genes RB1 (3/13 cancer types), NF1 (5/8), NF2 (1/2), PTEN (7/15), and BAP1 (2/6)." (PMID 34862370, 2021). "As such, the loss of RB1 promotes undifferentiated behaviors of cancer cells, though the extent to which tissue-specific transcription factors also contribute to this phenotype is still unclear." (PMID 34359636, 2021). "Of these, clinical data support acquisition of RB1 mutations in a minority of cancers progressing on CDK4/6i, with preexisting loss of functional RB1 associated with poor prognosis on CDK4/6i therapy." (PMID 32940689, 2021).